ENSG00000248223 (novel transcript)
Gene: Long non-coding RNA gene on chromosome 5 (17,353,910 to 17,362,633, forward strand). Ensembl gene ENSG00000248223.
Gene Ontology:
Biological process: response to iron ion